RNU4-45P (RNA, U4 small nuclear 45, pseudogene)
Gene: Small nuclear RNA gene on chromosome 21 (22,205,192 to 22,205,332, forward strand). Ensembl gene ENSG00000202339.
Homologues: Orthologues: chimpanzee U4 (99% identical), macaque U4 (90% identical). Paralogues in human: RNU4-68P (84% identical), RNU4-13P (84% identical), RNU4-67P (84% identical), RNU4-58P (83% identical), RNU4-7P (83% identical), RNU4-76P (80% identical), RNU4-8P (80% identical), RNU4-23P (79% identical), RNU4-35P (79% identical), RNU4-42P (79% identical), RNU4-44P (79% identical), RNU4-92P (79% identical), and 80 more.